MPO (myeloperoxidase)
Diseases named in the same sentence as MPO in open-access papers (continued):
Sharing a sentence is not in itself a finding about the gene and the disease.
Hyperkeratosis (2 papers, 2006 to 2023). Hyperkeratosis is a histopathological term defining a thickened stratum corneum and may be present in many different skin conditions, with many possible overlaps. "Both As and smoking are potent inducers of oxidative stress, and a recent small-scale study suggested that genetic susceptibility to oxidative stress, as determined by polymorphisms in the myeloperoxidase and catalase genes, is associated with elevated risk of developing As-related hyperkeratosis." (PMID 17185274, 2006). "The hyperkeratosis and a neutrophil infiltrate, with the related MPO release, that is induced in the skin of Nlrp3R258W mice with this treatment was significantly attenuated by ablating Zbtb16." (PMID 38123560, 2023).
hypertrophic cardiomyopathy (2 papers, 2019 to 2023). A condition in which the myocardium is hypertrophied without an obvious cause. "Salivary MPO was characterised by a downward trend with a significantly lower level than the baseline at 48 h after the alcohol septal ablation in patients with hypertrophic cardiomyopathy." (PMID 37569455, 2023).
Hypoglycemia (2 papers, 2012 to 2019). A decreased concentration of glucose in the blood. "Here, we found that DCA decreased IgG leakage in the whole brain and the number of MPO (+) cells in the hippocampus after hypoglycemia." (PMID 31052436, 2019). "Minocycline injection significantly reduced hypoglycemia-induced microglial activation and myeloperoxidase (MPO) immunoreactivity." (PMID 22998689, 2012).
ileus (2 papers, 2019 to 2021). Decrease in peristalsis in the absence of a mechanical bowel obstruction. "Administration with 5-HT4R agonists significantly reduced the number of infiltrated CD68-positive macrophages and MPO-stained neutrophils in the intestine of mice with postoperative ileus, and this was in agreement with previous results observed in rat models." (PMID 30971711, 2019). "In the postoperative ileus (POI) model, EA at ST36 decreased TNF-α and IL-6 concentration in serum and MPO activities in the intestine." (PMID 35095910, 2021).
infective endocarditis (2 papers, 2024). Infective endocarditis (IE) is an infection of the inner lining of the heart chambers (endocardium) and valves. "A limitation of our study is that we have not been able to exclude the presence of systemic malignancy or infective endocarditis with respect to elevated MPO-ANCA." (PMID 39569301, 2024).
Interstitial pneumonitis (2 papers, 2015 to 2022). "The patients with MPA in Japan had a higher age at onset, more frequent MPO-ANCA positivity, lower serum creatinine, and more frequent interstitial pneumonitis than those in Europe." (PMID 35566698, 2022).
intestinal infection (2 papers, 2020 to 2022). "An increase in neutrophil infiltration as a result of intestinal infection is associated with increased biomarkers such as MPO and LCN-2." (PMID 35882715, 2022). "Collectively, these data indicate that MCPIP-1 significantly inhibits IBD neutrophils to produce ROS and MPO, which may compose the defense of the intestine to resist against intestinal infection in IBD." (PMID 33488293, 2020).
ischemia reperfusion injury (2 papers, 2010 to 2021). Adverse functional, metabolic, or structural changes in ischemic tissues resulting from the restoration of blood flow to the tissue (reperfusion), including swelling; hemorrhage; necrosis; and damage from free radicals. "In addition, Cyclosporine A (CsA) in liposomal formulation (Lipo-CsA) inhibits the inflammation response, including myeloperoxidase (MPO) activity and TNF-α levels, in the model of ischemia reperfusion injury (I/R) cerebral injuries." (PMID 34122112, 2021). "As pre-treatment with Tanshinone IIA reduces TNF-α, the myeloperoxidase (MPO) marker of leukocytes, E-selectin and ICAM-1 in ischemic brain tissue and serum IL-8, Danshen may inhibit inflammatory responses to reduce brain damage induced by ischemia-reperfusion injury in rats." (PMID 20565944, 2010).
kidney injury (2 papers, 2019 to 2023). Trauma to the kidney. "Early developing anti-MPO immune responses were assessed at day 10 and both established immune responses and kidney injury were assessed following the induction of kidney injury as detailed previously." (PMID 36674855, 2023).
leprosy (2 papers, 2008 to 2024). Leprosy is a chronic infectious disease affecting primarily the skin and peripheral nervous system. "The presence of MPO, an azurophilic granule marker, indicates neutrophil activation, as demonstrated in leprosy, and formation of neutrophil extracellular traps in various models of inflammation." (PMID 39602398, 2024).
malignant hypertension (2 papers, 2021). Severe hypertension that is characterized by rapid onset of extremely high blood pressure and hypertension-mediated organ damage. "Therefore, our study, for the first time, shows effects of resveratrol on the MPO activity in heart tissue, particularly in the model of malignant hypertension, as well as the beneficial effects of resveratrol treatment in this model." (PMID 34066865, 2021). "Therefore, we attempted to assess granulocyte infiltration by staining for MPO; MPO-positive cells were observed exclusively in kidneys from animals with malignant hypertension." (PMID 34528115, 2021).
meningioma (2 papers, 2020 to 2026). A generally slow growing tumor attached to the dura mater. "This study integrated 16S rRNA sequencing of fecal samples from 15 treatment-naïve WHO grade I meningioma patients (MPs) and 15 healthy controls (HCs) with immunohistochemical profiling of tumor immune infiltrates (MPO+ neutrophils, CD68+ macrophages, CD3+ T cells)." (PMID 42059606, 2026).
metastasis (2 papers, 2023 to 2025). The spread or migration of cancer cells from one part of the body (where they first appeared) to another. "We also tested the clinical relevance of MPO‐DNA, and a high serological level was closely correlated with synchronous and subsequent liver metastasis and lower OS rates in patients with CRC." (PMID 37345586, 2023). "CD15+MPO− TANs also correlated inversely with skin metastasis (P = 0.020), a trend was seen for association between CD15−MPO+ (MPO+) cells and lung metastasis (P = 0.059), while CD15+MPO+ TANs showed a negative trend towards correlating with bone metastasis (P = 0.061)." (PMID 40652059, 2025).
metastatic melanoma (2 papers, 2013 to 2023). A melanoma that has spread from its primary site to another anatomic site. "We also found that the circulating levels of MPO, MMP-9, GM-CSF and CXCL8/IL-8 were higher in metastatic melanoma patients than in healthy controls." (PMID 37525065, 2023). "Furthermore, serum concentrations of neutrophil-related factors (MPO, MMP-9, CXCL8/IL-8 and GM-CSF) and NET biomarkers (nucleosomes and CitH3) were higher in stage IV metastatic melanoma patients than in healthy controls." (PMID 37525065, 2023).
Myocardial necrosis (2 papers, 2008 to 2015). Irreversible damage to heart tissue (myocardium) due to lack of oxygen after a heart attack (myocardial infarction). "Plasma levels of PTX3 seemed to reflect PTX3 gene expression in leukocytes, and plasma levels of MPO were significantly related to LVEF and myocardial necrosis." (PMID 28197227, 2015).
neuropathic pain (2 papers, 2021 to 2025). Chronic pain caused by damage to nerve fibers. "Therefore, we postulate that CCR3-targeted therapy will be beneficial to patients since its antagonist positively influences neuroimmune interactions by modulating MPO+ cell activation and influx in neuropathic pain." (PMID 34795678, 2021). "In paclitaxel-induced neuropathic pain model, gallic acid has been reported to have ameliorative effect by moderating TNF-α and myeloperoxidase (MPO) levels." (PMID 40969950, 2025).
non-alcoholic fatty liver disease (2 papers, 2012 to 2019). "MPO also catalyzes nitration of protein tyrosyl groups, which is associated with human non-alcoholic fatty liver disease (NAFLD) as well." (PMID 23285030, 2012). "The MPO enzyme catalyzes the conversion of hydrogen peroxide to hypochlorite and hypochlorous acid, and its activation has been related to the proapoptotic and profibrotic pathway of progression in non-alcoholic fatty liver disease." (PMID 31783479, 2019).
Opportunistic infection (2 papers, 2019 to 2021). An infection that is caused by a pathogen that would generally not be able to cause an infection in a host with a normal immune system. "An increased risk of opportunistic infections due to inhibition of myeloperoxidase in neutrophil granules was not anticipated at this level of AZD4831 exposure." (PMID 30618054, 2019). "These granules comprise various defensive factors and enzymes, such as myeloperoxidase (MPO), elastase, defensins, cathelicidins, and matrix metalloproteinases (MMPs), which protect against opportunistic infections and mediate the alleviation of inflammation." (PMID 34484197, 2021).
osteosarcoma (2 papers, 2020 to 2025). A usually aggressive malignant bone-forming mesenchymal neoplasm, predominantly affecting adolescents and young adults. "Furthermore, COLEC12 knockdown could increase inflammation of osteosarcoma, in vivo and in vitro, through inducing myeloperoxidase (MPO), TLR4, NF‐κB, and C3, and expression of related inflammatory factors." (PMID 32822099, 2020).
pericarditis (2 papers, 2020 to 2024). An inflammatory process affecting the pericardium. "The pro-inflammatory effects (increase in CRP and IL-6) and oxidative stress (MPO and ROS) intrinsic to ablation have been connected to early AF recurrence and pericarditis." (PMID 39156919, 2024).
plaque psoriasis (2 papers, 2020 to 2021). "Here, we asked whether MPO plays a pathogenic role in plaque psoriasis using the Imiquimod (IMQ) mouse model that induces an innate immune response in the skin via its activity as a toll-like receptor (TLR) 7 agonist." (PMID 34572970, 2021). "We found that both MPO deficiency and inhibition resulted in attenuated plaque psoriasis severity." (PMID 34572970, 2021). "Current therapies for plaque psoriasis target many facets of the autoimmune response, but there is an incomplete understanding of how oxidative damage produced by enzymes such as myeloperoxidase contributes to skin pathology." (PMID 34572970, 2021). "In this study, we used the Aldara (Imiquimod) cream model of plaque psoriasis in mice to assess myeloperoxidase inhibition for treating psoriatic skin lesions." (PMID 34572970, 2021). "Although studies have increasingly suggested that oxidative damage plays a role in plaque psoriasis, it is not known to what extent MPO contributes to overall oxidative stress in this disease." (PMID 34572970, 2021).
polyneuropathy (2 papers, 2020 to 2023). A disease or disorder affecting more than one nerve. "In this case, the diagnosis was done based on peripheral eosinophilia, polyneuropathy, imaging findings of the lung on CT and was strongly supported with positive P-ANCA and presence of MPO 5 antibody." (PMID 33391913, 2020).
polyp (2 papers, 2023 to 2025). A usually exophytic mass attached to the underlying tissue by a broad base or a thin stalk. "Previous results were confirmed through protein measurements of ECP, from eosinophil granules, and myeloperoxidase (MPO), from neutrophil granules, in polyp tissue." (PMID 41311116, 2025).
Primary Immunodeficiency (2 papers, 2017 to 2024). "Indeed, because myeloperoxidase (MPO) deficiency is generally considered to be innocuous it has been removed as a primary immune deficiency disease as classified by the Primary Immunodeficiency Diseases Classification Committee of the International Union of Immunological Societies." (PMID 28982143, 2017). "MPOD is a primary immunodeficiency characterised by decreased MPO activity in neutrophils." (PMID 39421445, 2024).
proliferative glomerulonephritis (2 papers, 2014 to 2025). A constellation of renal disorders characterized by an increase number of cells in the glomerulus; these disorders generally present with nephrotic syndrome, and generally progress to end stage renal failure over a matter of weeks to years, depending on the etiology. "In principle, MPO-specific T-cells bear the potential to induce proliferative glomerulonephritis in planted-antigen models." (PMID 40821760, 2025).
reactive arthritis (2 papers, 2018 to 2025). Reactive arthritis (ReA) is an autoimmune disorder belonging to the group of seronegative spondyloarthropathies and is characterized by the classic triad of arthritis, urethritis and conjunctivitis. "The neutrophil protein, myeloperoxidase, was present in all fluid samples except fluid F6, which came from a patient with suspected reactive arthritis, and did not contain streptococcal DNA." (PMID 29654237, 2018).
Respiratory tract infection (2 papers, 2024). An infection of the upper or lower respiratory tract. "Observational researches reported the underlying correlation of plasma myeloperoxidase (MPO) concentration with respiratory tract infections (RTIs), but their causality remained unclear." (PMID 38576857, 2024).
rhabdomyolysis (2 papers, 2019 to 2022). Necrosis or disintegration of skeletal muscle often followed by myoglobinuria. "Exertional rhabdomyolysis after unaccustomed eccentric exercise may be related to underlying inability to resolve intramuscular MPO." (PMID 30804809, 2019).
RSV bronchiolitis (2 papers, 2009 to 2020). "It is recognized that the inflammatory processes in the airways of infants with RSV bronchiolitis are dominated by an intense neutrophil influx and that neutrophil products, such as MPO and NE, are released into the airway lumen." (PMID 32295918, 2020). "Blood neutrophils had more CD11b in preterm and term infants with RSV bronchiolitis than control infants (p<0.025) but similar amounts of MPO." (PMID 19497921, 2009). "BAL fluid neutrophils from infants with RSV bronchiolitis had greater amounts of CD11b and MPO than blood neutrophils and BAL fluid neutrophils from controls (p<0.01)." (PMID 19497921, 2009). "For both groups of infants with severe RSV bronchiolitis, there were greater amounts of CD11b and MPO in neutrophils from the BAL fluid than from the blood." (PMID 19497921, 2009).
schizophrenia (2 papers, 2020 to 2025). A major psychotic disorder characterized by abnormalities in the perception or expression of reality. "Possible explanations for these results are, typical antipsychotics may cause an increase in oxidative stress by increasing MPO levels, or increased MPO is a trait of schizophrenia and typical antipsychotics fail to decrease it." (PMID 41300145, 2025). "We aimed to investigate serum myeloperoxidase (MPO), catalase (CAT), and malondialdehyde (MDA) levels and their diagnostic value in schizophrenia." (PMID 41300145, 2025). "Based on prior literature, this study aimed to investigate MPO and CAT levels and their diagnostic value in schizophrenia patients." (PMID 41300145, 2025). "This study is an investigation that individually compares MPO levels in schizophrenia patients receiving typical, atypical, and combined antipsychotic treatments with those of healthy controls." (PMID 41300145, 2025). "From this scope, increased MPO activity in schizophrenia patients and correlation between MPO and PANSS-N scores may be important in terms of suggesting a possible biochemical association between negative symptoms of schizophrenia and MPO." (PMID 41300145, 2025). "Furthermore, increased MPO levels have been reported in schizophrenia." (PMID 41300145, 2025). "Increased MPO could be important in terms of representing probable association between negative symptoms of schizophrenia and oxidation-inflammation." (PMID 41300145, 2025). "Importantly, MPO showed a significant correlation with negative symptom severity, suggesting a possible biochemical association between oxidative stress and the core psychopathology of schizophrenia." (PMID 41300145, 2025). "In this study, we demonstrated that serum MDA, MPO, and CAT levels were significantly elevated in schizophrenia patients compared with healthy controls." (PMID 41300145, 2025). "In contrast to MPO, CAT has been widely investigated in schizophrenia, with decreased, unaltered, and increased levels reported." (PMID 41300145, 2025). "Essential findings of our study are as following: increased MDA, MPO and CAT levels in overall schizophrenia patients and subgroups of patients." (PMID 41300145, 2025). "In brief, we found MPO, CAT and MDA were increased in schizophrenia patients." (PMID 41300145, 2025).
Sciatica (2 papers, 2021). Pain in the lower back and hip radiating in the distribution of the sciatic nerve. "Network analysis identified TLR4, MMP9, MPO, CAMP, RETN and TLR5 as key genes contributing to the dysregulation of genes in the peripheral blood of patients with sciatica." (PMID 33535986, 2021). "Combining these studies, a potential link between TLR4, MMP9, MPO, CAMP, RETN, and sciatica can be established, but microarray analysis showed that the expression of these genes was not changed after integrated TCM treatment." (PMID 33573686, 2021). "The PPI network suggested that TLR4, MMP9, MPO, CAMP, RETN, TLR5, and IL1RN were key genes in the dysregulation of genes in the peripheral blood of patients with sciatica." (PMID 33573686, 2021). "Consistent with the microarray data, the expression levels of the key genes (TLR4, MMP9, MPO, CAMP, RETN and TLR5) were significantly increased in patients with sciatica compared with healthy controls." (PMID 33535986, 2021). "Bioinformatic analysis revealed that most of the DEGs-baseline were related to immunity and the inflammatory response and that TLR4, MMP9, MPO, CAMP, RETN, TLR5, and IL1RN were key genes involved in the dysregulation of genes in the peripheral blood of patients with sciatica." (PMID 33573686, 2021).
shigellosis (2 papers, 2020 to 2026). Shigellosis is a bacterial infection leading to dysentery and is caused by Shigella, which are small, ubiquitous Gram-negative bacteria belonging to the enterobacteria family. "Signs of disease in WT-infected mice peaked between 2 and 3 days post-infection with weight loss, stool consistency, and MPO signal returning to baseline levels at approximately seven days post-infection, consistent with the disease progression and resolution of human shigellosis." (PMID 33074100, 2020).
spondyloarthritis (2 papers, 2020 to 2025). "Recent proteomic analysis of SF from RA patients and spondyloarthritis (SpA) patients identified elevated levels of many neutrophil proteins in RA SF, including MPO, cathepsin G, annexin-A1 and NGAL." (PMID 33469455, 2020).
squamous cell carcinoma (2 papers, 2018 to 2020). A carcinoma arising from squamous epithelial cells. "In squamous cell carcinoma, RvD2 decreases the infiltration of neutrophils and suppresses myeloperoxidase (MPO) activity." (PMID 33613558, 2020).
subarachnoid haemorrhage (2 papers, 2022 to 2024). "In experimental studies, MPO deficiency prevents the development of delayed cognitive impairment (DCI) after subarachnoid haemorrhage." (PMID 35175161, 2022). "The findings revealed that in the myocardium of subarachnoid haemorrhage patients, the number of myeloperoxidase‐positive cells was significantly higher than it was in controls." (PMID 38896112, 2024). "In a histopathologic study, the myocardium of 25 patients who died of subarachnoid haemorrhage and 18 controls was stained with antibodies identifying neutrophil granulocytes (myeloperoxidase)." (PMID 38896112, 2024).
T-cell lymphoma (2 papers, 2012 to 2015). "Since MS may express T-cell markers (such as CD43, CD45, CD4, and CD7), immunohistochemical expressions of MPO, lysozyme, and CD68 should be analyzed for their distinction from T-cell lymphomas." (PMID 25805673, 2015).